CCL1 (C-C motif chemokine ligand 1)
Description:
Cytokine that is chemotactic for monocytes but not for neutrophils. Binds to CCR8.
Synonyms: SCYA1; I-309; TCA3; P500; SISe
Tractability: Antibody: its Gene Ontology location is reachable by antibodies, with high confidence; UniProt places it where antibodies can reach, with medium confidence; UniProt predicts a signal peptide or a membrane-spanning region.
Gene: Protein-coding gene on chromosome 17 (34,360,328 to 34,363,233, reverse strand). Ensembl gene ENSG00000108702.
Subcellular location: Secreted
Pathways (Reactome):
Signal Transduction: Chemokine receptors bind chemokines; G alpha (i) signalling events
Gene Ontology:
Molecular function: chemokine activity; CCR chemokine receptor binding; cytokine activity
Biological process: positive regulation of cytosolic calcium ion concentration; positive regulation of inflammatory response; positive regulation of interleukin-17 production; positive regulation of monocyte chemotaxis; antimicrobial humoral immune response mediated by antimicrobial peptide; chemokine-mediated signaling pathway; chemotaxis; eosinophil chemotaxis; inflammatory response; intracellular calcium ion homeostasis; positive regulation of cell migration; signal transduction; viral process; immune response
Cellular component: extracellular region
Genetic constraint (gnomAD): Loss-of-function variants: 8 observed, 4.77 expected, observed/expected ratio (o/e) 1.68, 90% interval 0.89 to 1.95. That is too few expected variants to judge how well the gene tolerates losing a copy. Missense variants: 94 observed, 105.97 expected, observed/expected ratio (o/e) 0.89, 90% interval 0.75 to 1.05. Synonymous variants: 44 observed, 42.78 expected, observed/expected ratio (o/e) 1.03, 90% interval 0.81 to 1.32.
Homologues: Orthologues: chimpanzee CCL1 (98% identical), macaque CCL1 (82% identical), zebrafish ccl35.1 (27% identical), zebrafish ccl35.2 (27% identical). Paralogues in human: CCL11 (34% identical), CCL3L3 (34% identical), CCL7 (34% identical), CCL13 (33% identical), CCL3 (33% identical), CCL8 (33% identical), CCL15 (32% identical), CCL24 (32% identical), CCL2 (30% identical), CCL22 (30% identical), CCL4 (30% identical), CCL14 (29% identical), and 14 more.
Diseases named in the same sentence as CCL1 in open-access papers:
CCL1 is named in the same sentence as 123 diseases in open-access papers, as found by Europe PMC text mining. Sharing a sentence is not in itself a finding about the gene and the disease. The quoted sentences say what the papers report.
breast cancer (18 papers, 2015 to 2025). A primary or metastatic malignant neoplasm involving the breast. "The expression of CCL1 is consistently increased in breast cancer, and there exists a positive association between CCL1 levels and the infiltration of CCR8+ regulatory T cells." (PMID 38730579, 2024). "For instance, CCL1 derived from tumor-associated macrophages promotes breast cancer metastasis through activating NF-κB/SOX4 signaling." (PMID 34108990, 2021). "Surprisingly, there was causal association between CCL1 and breast cancer in bi-MR analysis." (PMID 38075694, 2023). "For CCL chemokines, previous studies had shown that CCL1 mainly recruits Tregs to change the tumor microenvironment and promote the progression of breast cancer stem cells." (PMID 38075694, 2023). "Survival and Cox analyses of all the DEGs confirmed CCL1 and MYH6 were independent protective factors and IFNK and SOAT2 were independent risk factors for basal-like breast cancer (95%CI: 1.06–2.5, p = 0.026)." (PMID 36694223, 2023). "In bi-MR, the causal association between CCL1 [OR (95%CI), 0.94 (0.89–0.99), p = 0.020] and CCL18 [OR (95%CI), 0.94 (0.89–1.00), p = 0.034] and breast cancer (finn-b-C3_BREAST) was found." (PMID 38075694, 2023). "As a result, targeting CCR8+ Treg cells through anti-CCR8 mAb or anti-CCL1 neutralizing mAb provides an opportunity for the selective depletion of Treg cells as an immunotherapeutic approach for the treatment of breast cancer." (PMID 34868991, 2021). "For this reason, chemokines such as CCL1/I-309 (in breast cancer), CCL17/TARC, CCL22/MDC (in gastric cancer and hepatocellular carcinoma), and CCL28/MEC (in hepatocellular carcinoma) cause Treg recruitment into the tumor niche." (PMID 33114763, 2020). "Its role in shaping the tumor microenvironment was recently demonstrated by the fact that CCL1 blockade in murine breast cancer models led to reduced Treg numbers." (PMID 30572845, 2018). "Taken together, CCL1 expressing immune cells and FoxP3+ Treg are significantly increased in invasive breast cancer tissues compared to healthy breasts." (PMID 30572845, 2018). "CCL1 has been described to be expressed by breast cancer stem cells and has been found to impact Treg migration in murine breast cancer models." (PMID 30572845, 2018). "It was shown that Sox2-mediated CCL1 expression in murine breast cancer models was related to a higher infiltration by Treg and CCL1 overexpression led to an increase of Treg accumulation." (PMID 30572845, 2018). "In order to investigate the role of CCL1 and CCL22 on Treg infiltration and overall survival in breast cancer patients, we stained tissue microarrays of 199 breast cancer patients for the CCL1, CCL22 and FoxP3." (PMID 30572845, 2018). "Amongst these, CCL1 has been described to play a role on Treg de novo conversion and Treg recruitment to murine breast cancer models." (PMID 30572845, 2018). "We stained tissue microarrays (TMA) of 199 breast cancer patients for expression of CCL1, CCL22 and FoxP3." (PMID 30572845, 2018). "In order to determine the role of CCL1 and CCL22 on Treg attraction to breast cancer, we analyzed 199 breast cancer tissue samples that were previously stained for expression of CCL1, CCL22 and FoxP3." (PMID 30572845, 2018). "We found a significantly increased expression of CCL1 in breast cancer tissues, which was related to a higher infiltration of Treg." (PMID 30572845, 2018). "Strikingly, we found significantly increased numbers of CCL1 and FoxP3 expressing cells in breast cancer tissues compared to normal breast tissues." (PMID 30572845, 2018). "CCL1 was highly upregulated in breast cancer, positively correlated with Treg infiltration and high grade tumors, whereas none of these was found for CCL22." (PMID 30572845, 2018). "In addition, there was a reverse causal association between CCL1 (OR = 0.94) and CCL18 (OR = 0.94) and breast cancer." (PMID 38075694, 2023). "As shown in MR Results, CCL1 and CCL2 were risk factors for breast cancer." (PMID 38075694, 2023).
breast cancer (continued). "Moreover, the I-309/CCL1 was highly expressed in human breast cancer; in addition, the high expression of this chemokine correlated with the infiltration of immunosuppressive FoxP3+ Tregs, which negatively affect patient survival." (PMID 36354566, 2022). "Neu+ mammary tumor line secreted G-csf, Ccl-1, Ccl-5, Cxcl-1, Cxcl-2, Cxcl-10, and Il-1ra." (PMID 31941005, 2020). "Our data highlight the role of CCL1 on Treg migration into breast cancer tissue, a finding that might lead to novel therapeutic strategies in breast cancer immunotherapy." (PMID 30572845, 2018). "We conclude that CCL1 might offer new interesting starting points for immunotherapy in breast cancer." (PMID 30572845, 2018). "A more extensive analysis might thus unravel the role of CCL1 mediated Treg recruitment on breast cancer patient survival." (PMID 30572845, 2018). "Additionally, the study suggests that CCL1 could potentially serve as a viable therapeutic target for the treatment of breast cancer." (PMID 38730579, 2024). "We further constructed a four-gene signature comprising CCL1, IFNK, MYH6, and SOAT2 genes, which shows a promising predictive value for basal-like breast cancer and may be related to the underlying Th1/Th2 balance regulation mechanism, which is worthy of further study." (PMID 36694223, 2023). "Thus, CCL1 serves as a prognostic marker and novel therapeutic target in breast cancer." (PMID 35057823, 2022). "In breast cancer, tumour‐derived chemokines such as CCL22 and CCL1 bind to CCR4 and CCR8 on Tregs, guiding their migration into tumour tissues." (PMID 41200753, 2025). "As shown in breast cancer research studies, these cells in the tumor niche express CCR8 (receptor for CCL1/I-309) and CCR4 (receptor for CCL17/thymus and activation regulated chemokine (TARC) and CCL22/macrophage derived chemokine (MDC))." (PMID 33114763, 2020). "Thus, CCL1 may serve as prognostic marker and novel therapeutic target in breast cancer." (PMID 30572845, 2018). "The aim of this study was to identify the role of the two major Treg-attracting chemokines CCL1 and CCL22 in human breast cancer." (PMID 30572845, 2018). "CCL1, MYH6, IFNK, and SOAT2 have an independent prognostic value of survival outcome and might be novel markers in basal-like breast cancer." (PMID 36694223, 2023). "Both CCL1 and CCL22 were expressed in most breast cancer tissues." (PMID 30572845, 2018). "We found CCL1, CCL22, and FoxP3 expressing cells in most breast cancer tissues analyzed." (PMID 30572845, 2018). "Surprisingly, our data showed upregulation of CCL1 in breast cancer tissues, whereas CCL22 expression was not elevated when compared to normal breast tissue and did not correlate with Treg infiltration." (PMID 30572845, 2018). "Interestingly in immune-competent mouse models of breast cancer, regulatory T cells enhance SOX2 expression by mammary cancer cells in a paracrine manner, while Sox2-expressing tumor cells recruit Tregs through NF- κB/CCL1 [Nuclear Factor kappa B/Chemokine (C-C motif) ligand 1] signaling." (PMID 33553286, 2020). "Thus, in breast cancer, CCL1 rather than CCL22 seems to impact Treg migration and could affect patient survival." (PMID 30572845, 2018). "Cochrane’s Q test did not provide evidence of heterogeneity between CCL1 (p = 0.227), CCL2 (p = 0.982), CCL18 (p = 0.221), CXCL5 (p = 0.533), CXCL12 (p = 0.977), and CXCL13 (p = 0.520) and breast cancer." (PMID 38075694, 2023). "Cochrane’s Q test did not provide evidence of heterogeneity between CCL1 (p = 0.675) and CCL18 (p = 0.336) and breast cancer." (PMID 38075694, 2023).
colitis (12 papers, 2013 to 2025). Inflammation of the colon. "In DSS colitis CD69−/− CD4 T cell accumulation in colonic lamina propria (cLP) was associated with increased expression of CCL-1, CXCL-10 and CCL-19 genes." (PMID 23776480, 2013). "Notably, Ccl1 has been linked to improved outcomes in DSS colitis models by inducing IFNγ expression in ILCs61." (PMID 41041542, 2025). "Interestingly, mice overexpressing CCL1 showed significantly less colitis-dependent weight loss consistent with reduced endoscopic and histological signs of disease." (PMID 33613532, 2020). "Conversely, CCL1 treated mice displayed similar susceptibility to mucosal damage as control-treated Ccr8−/− mice consistent with a gut protective functional role of CCL1/CCR8 signaling during experimental colitis." (PMID 33613532, 2020). "In DSS colitis model this was at least partially dependent on the increased expression levels of the chemokines CCL-1, CXCL-10 and CCL-19 in the colon of CD69-deficient animals, as neutralization of these three chemokines significantly improved the histopathological picture in colon." (PMID 23776480, 2013). "Although the present study did not detect alterations in CXCL13 and CXCR5 expression in MLB cells from TNBS-induced colitis rats, we observed upregulated mRNA expression of Ccr8, a receptor for the T cell-derived chemokine Ccl1, in these rats." (PMID 40331987, 2025). "Mechanistically, MLB cells from colitis rats were recruited to the colon by intra-intestinal T cells through the Ccr8-C-C motif chemokine ligand 1 (Ccl1) axis, where they subsequently exacerbated inflammatory responses via enhanced differentiation." (PMID 40331987, 2025). "Colonic CD4+ T cells isolated from normal control rats and TNBS-induced colitis rats were seeded into the lower chamber of a Transwell system and treated with either control siRNA or si-Ccl1-3 for 24 h." (PMID 40331987, 2025). "Consistently, a prior study has reported that M2-EVs can alleviate intestinal inflammation in DSS-induced colitis by mediating the CCL1/CCR8 axis." (PMID 34895044, 2021). "Further experiments revealed that this gut protective function of CCR8 seems to be selectively mediated by the chemotactic ligand CCL1, which was particularly produced by intestinal macrophages during colitis." (PMID 33613532, 2020). "The M2b macrophage exosomes exerted protective effects on DSS-induced colitis, mainly mediated by the CC chemokine 1 (CCL1)/CCR8 axis." (PMID 31749791, 2019). "The results also suggest that M2b macrophage exosomes exert protective effects in DSS-induced colitis, which are mainly mediated by the CCL1/CCR8 axis." (PMID 31749791, 2019). "Many of the inflammatory cytokines attenuated by FFAR2 and FFAR3, including C5, CCL1, CCL2, GM-CSF, IL-1α, IL-1β, ICAM-1 and TNF, are associated with colitis." (PMID 27667443, 2016). "Furthermore, the increased mRNA expression of Ccl1 was also observed in the colon of TNBS-induced colitis rats." (PMID 40331987, 2025). "In further experiments, we also analyzed, whether increased in vivo concentrations of CCL1 or CCL8 affected the mucosal frequencies of IFN-γ producing ILCs in the lamina propria of mice with DSS colitis." (PMID 33613532, 2020). "To establish further evidence that the protective role of CCL1/CCR8 signaling during acute colitis is primarily driven by innate immune system mediated mechanisms, we overexpressed CCL1 in lymphopenic Rag1−/− mice, which lack T and B cells, but harbor a functional ILC compartment." (PMID 33613532, 2020). "Indeed, in the colitis model, activation of the CCL1/CCR8 system is limited to the serosal side of the colon or the peritoneal cavity." (PMID 24714157, 2014). "Severity of the colitis could be ameliorated in DSS-administrated CD69-deficeint mice with the neutralization of CCL-1, CXCL-10 and CCL-19." (PMID 23776480, 2013).
colitis (continued). "Notably, flow cytometry studies identified intestinal macrophages as important producer of CCL1 compared to ILC2s or regulatory T cells or other important immune cells within LPMC of mice with DSS colitis confirming previous results that found CCL1 protein in exosomes of gut-derived M2 macrophages." (PMID 33613532, 2020). "In this study here, we explored the functional role of the CC chemokine receptor CCR8 and its activation by the two known ligands CCL1 and CCL8 in DSS colitis, a widely used mouse model of IBD resembling important features of UC." (PMID 33613532, 2020). "To ascertain the individual capacity of both CCR8 ligands to regulate mucosal damage during acute colitis, we studied in the next series of experiments the development of DSS colitis in the absence or presence of systemic CCL1 or CCL8 overexpression." (PMID 33613532, 2020). "CD69-deficient mice showed increased transcript levels of some chemokine genes, such as CCL-1, CXCL-10 and CCL-19 in steady-state conditions and after colitis induction." (PMID 23776480, 2013). "In addition, the expression of CCR8 and its ligand CCL1 is upregulated in patients with UC and in the DSS-induced colitis model." (PMID 35707544, 2022). "Interestingly, further experiments clearly suggested that these CCR8-mediated tissue protective effects are exclusively mediated by the ligand CCL1, while CCL8-treatment of wildtype mice rather exacerbated colitis." (PMID 33613532, 2020). "Moreover, increased CCL1 and CCL8 protein concentrations were present in supernatants of stimulated lamina propria mononuclear cells (LPMCs) isolated from mice with DSS colitis." (PMID 33613532, 2020). "Additionally, we found that M2b macrophage exosomes, carrying the CCL1 protein to the colon, interact with CCR8 to promote Th2 polarization and increase Treg percentages, thereby relieving colitis." (PMID 31749791, 2019). "In the case of colitis, the potential for R243 to block both CCL2 (MCP-1)/CCR2-driven chemotaxis and CCL1 might enhance the anti-inflammatory effect in comparison with that of CCR8-/- mice." (PMID 24714157, 2014). "Furthermore, treatment of DSS-administrated CD69−/− mice with the mixture of CCL-1, CXCL-10 and CCL-19 neutralizing Abs significantly decreased the histopathological signs of colitis." (PMID 23776480, 2013). "The treatment of DSS-induced colitis in CD69−/− mice with the mixture of Abs that neutralize CCL-1, CXCL-10 and CCL-19 did not affect the accelerated body weight loss, but it reduced significantly the histopathological severity of the disease." (PMID 23776480, 2013). "Therefore, we questioned whether M2b macrophage exosomes carrying the CCL1 protein to the colon, interact with the CCR8 receptor to regulate Th2 polarization and Treg cells, and thereby attenuate DSS-induced colitis." (PMID 31749791, 2019). "Unlike parasite infection, the major source of CCL1 during DSS-induced colitis is macrophages rather than ILC2s, but CCL1/CCR8 signaling similarly protects hosts from both parasite infection and acute intestinal damage in a DSS colitis model." (PMID 35707544, 2022).
COVID-19 (10 papers, 2021 to 2025). A disease caused by infection with severe acute respiratory syndrome coronavirus 2. "Mean levels of CCL1, CXCL10, IL-1ra, IL-6, IL-8 and IL-16 as well as Serpin E1 and C5/C5a are elevated in the CSF of COVID-19 patients compared to non-neurological controls." (PMID 36759861, 2023). "We found that plasma exosomes from COVID-19 patients significantly induced the production of the same set of cytokines and chemokines that contribute to the severity of COVID-1949–53, including IL-6, IL-8, TNF-α, IFNγ, CCL1, and GDF-15, in PBMCs compared with those from non-COVID donors." (PMID 36526691, 2022).